SDC1 (syndecan 1)
Diseases named in the same sentence as SDC1 in open-access papers (continued):
Sharing a sentence is not in itself a finding about the gene and the disease.
gastric cancer (24 papers, 2008 to 2025). A primary or metastatic malignant neoplasm involving the stomach. "Loss of epithelial SDC1 expression as well as high stromal SDC1 expression was associated with unfavorable prognosis in gastric cancer." (PMID 26293675, 2015). "The loss of epithelial syndecan-1 and strong stromal syndecan-1 was associated with an unfavorable prognosis in gastric cancer." (PMID 23691363, 2013). "In agreement with other analyses of gastric carcinoma, loss of epithelial syndecan-1 correlated with tumor TNM stage and incidence of metastases to local lymph nodes." (PMID 19865524, 2009). "Later on during the progress of tumor microevolution, the malignant clone apparently takes advantage of the loss of cell surface syndecan-1, as observed through the connection between decreased cell surface syndecan-1 levels and unfavorable prognosis in head and neck tumors and gastric cancers." (PMID 32388727, 2020). "Some PGs have also been studied in EBV-associated cancers and premalignant conditions: chondroitinsulfate proteoglycan CD44 is detected in EBV-associated NPC and EBV-related gastric carcinoma; syndecan-1 (CD138) has been suggested to play a role in EBV-related PTLD." (PMID 26527314, 2015). "Thus, in gastric cancers, tumor cell expression of syndecan-1 has been correlated with patient survival and the loss of syndecan-1 with a poor prognosis." (PMID 18590537, 2008). "This study aimed to compare the effects of volatile anesthesia and total intravenous anesthesia (TIVA) on syndecan-1 shedding in patients with gastric cancer undergoing minimally invasive gastrectomy." (PMID 33452350, 2021). "The proteoglycans syndecan-1, syndecan-2, syndecan-4, glypican-1 and glypican-3 were upregulated in gastric cancer with high in vitro and in vivo peritoneal seeding potential, suggesting a role for these molecules in peritoneal dissemination." (PMID 27074785, 2016). "Other studies have shown that in breast, ovarian, and gastric cancer, the loss in cancer cell SDC-1 is accompanied by increased stromal SDC-1 expression and adverse clinical outcome." (PMID 21655218, 2011). "In accordance, downregulation of EDN1 expression dampened endothelial cell tube formation in human gastric cancer cells, implying that Sdc-1 may modulate angiogenesis via modulation of EDN1 expression." (PMID 34066023, 2021). "Ectopic expression of syndecan-1 in stromal cells has been reported in carcinomas of the cervix, and stromal syndecan-1 expression was shown to correlate with poor prognosis in some tumor types such as cancers of the stomach, pancreas, endometrium, oral cavity, breast, bladder, and ovary." (PMID 32977498, 2020). "Hence, this randomized controlled trial aimed to compare the effect of volatile anesthesia with sevoflurane/remifentanil and of total intravenous anesthesia (TIVA) with propofol/remifentanil on syndecan-1 shedding in patients with gastric cancer undergoing laparoscopic or robotic gastrectomy." (PMID 33452350, 2021). "Therefore, stromal and epithelial SDC1 expression might have some prognostic impact in gastric cancer." (PMID 26293675, 2015). "In gastric cancer, patients with SDC1-positive stroma had a worse outcome than patients with SDC1-negative stroma." (PMID 24373193, 2013).
Infertility (24 papers, 2016 to 2025). "This review comprehensively examines the role of endometrial CD-138 (syndecan-1) in the context of infertility and early pregnancy." (PMID 38529432, 2024).
acute kidney injury (23 papers, 2017 to 2026). Sudden and sustained deterioration of the kidney function characterized by decreased glomerular filtration rate, increased serum creatinine or oliguria. "Higher plasma levels of syndecan-1 were further associated with the development of acute kidney injury during the hospital stay." (PMID 40429565, 2025). "In liver transplantation, plasma syndecan-1 rises sharply after reperfusion and has been associated with postoperative acute kidney injury." (PMID 41303775, 2025). "In knowlesi malaria increased syndecan-1 was associated with acute kidney injury, after controlling for age and parasitemia." (PMID 33963210, 2021). "Higher plasma syndecan-1 levels by quartile were also significantly associated with hepatic failure (p < 0.001), renal failure (p = 0.004), and coagulation failure (p = 0.004) at study enrollment as defined by Brussels organ failure scoring." (PMID 28986821, 2017). "In addition, the prediction of acute kidney injury in a risk-stratified statistical model of clinical outcome was improved after adding urinary syndecan-1." (PMID 34540845, 2021). "Several other studies have also reported that an increased syndecan-1 concentration in the blood is associated with increased morbidity and mortality, including increased vasopressor use, acute kidney injury, and respiratory failure in patients undergoing surgery or in those with critical illness." (PMID 33915859, 2021). "Postoperative urinary syndecan-1 was collected within 2 h after surgery and was higher in patients suffering from acute kidney injury in the follow-up." (PMID 34540845, 2021). "Syndecan-1 is found in the endothelial glycocalyx and is released into the bloodstream during stressed conditions, including severe diseases such as acute kidney injury, chronic kidney disease, and cardiovascular disease." (PMID 34879094, 2021). "Among multiple organ failures, coagulation failure and renal failure were significantly correlated with serum syndecan-1." (PMID 34557532, 2021). "Main outcome measures included inflammatory and endothelial biomarkers (IL-6, IL-8, angiopoietin-2, syndecan-1), body fluid composition assessed by bioelectrical impedance, and clinical outcomes, including acute kidney injury (AKI), ICU length of stay (LOS), and ICU mortality." (PMID 41938900, 2026). "Another component of the glycocalyx, syndecan-1, was measured as a marker for glycocalyx disintegration in patients with acute decompensated heart failure admitted to the hospital and was predictive of the development of acute kidney injury and mortality." (PMID 40429565, 2025). "Similarly, in a prospective clinical study of 201 patients with acute decompensated heart failure, high syndecan-1 levels were predictive of acute kidney injury during hospitalization (duration: 8.4 ± 6.5 days)." (PMID 33915859, 2021). "Notably, the postoperative increase in the syndecan-1 concentration was related to the occurrence of postoperative complications, such as hypotension requiring vasopressor support, acute kidney injury, and desaturation." (PMID 33915859, 2021). "As syndecan-1 was found to enhance acute kidney injury in a previous report, our present findings suggested that the relationship between BUN and syndecan-1 might reflect slight kidney injury." (PMID 31462009, 2019). "A recent study showed that syndecan-1 may emerge as an early predictive biomarker for acute kidney injury (AKI) among patients admitted for acute HF." (PMID 37109427, 2023). "However, the syndecan-1 levels in patients who developed acute kidney injury (AKI) were higher than in those who did not (193 ng/mL [IQR 63–441] vs 93 ng/mL [IQR 23–187], p < 0.001)." (PMID 30654825, 2019).
plasma cell neoplasm (23 papers, 2006 to 2026). A clonal proliferation of immunoglobulin-secreting plasma cells. "Syndecan-1 (CD138) expression in different cancers is of upcoming clinical interest as precise drugs targeting CD138 are now being evaluated in clinical trials, particularly in plasma cell neoplasms." (PMID 38022112, 2023).
triple-negative breast carcinoma (23 papers, 2011 to 2025). An invasive breast carcinoma which is negative for expression of estrogen receptor (ER), progesterone receptor (PR), and human epidermal growth factor receptor 2 (HER2). "Zhong found that low SDC1 expression in CAFs in triple-negative breast cancer was linked to poor survival due to TIL cell infiltration." (PMID 41364407, 2025). "Our bioinformatics analysis revealed that SDC1 is significantly overexpressed in triple-negative breast cancer (TNBC) and is strongly associated with poor patient prognosis." (PMID 41209699, 2025). "This suggests that SDC1 may not only be used as a risk factor for triple-negative breast cancer in the elderly, but also by inducing cellular senescence in the TME." (PMID 41209699, 2025). "Similarly, in triple-negative breast cancer patients, an association between syndecan-1 and EGFR overexpression has been found." (PMID 34680238, 2021). "SDC1 has emerged as a regulator of CSCs phenotype in triple-negative breast cancer, where SDC1 gene silencing in MDA-MB-231 cells causes a downregulation in several components of the IL-6/STAT3, Notch, EGFR, and LRP6 pathways." (PMID 36358747, 2022). "We previously found that the depletion of Sdc-1 in the triple-negative breast cancer MDA-MB-231 cell line leads to an increase in migration and invasion which was dependent on the expression and activity of Rho-GTPase." (PMID 35155241, 2022). "Overall, these data point at an important role of Sdc-1 as a tumor suppressor, particularly in triple-negative breast cancer." (PMID 34070901, 2021). "We conclude that Sdc-1 knockdown differentially affects HA metabolism in luminal and triple-negative breast cancer model cell lines and impacts the stem phenotype, cell survival, and angiogenic factors." (PMID 34070901, 2021). "Overexpression of SDC1 correlates with tumor aggressiveness and poor survival in triple-negative breast carcinoma." (PMID 32916872, 2020). "Therefore, we investigated the potential impact of SDC1 on the immune microenvironment of triple-negative breast cancer." (PMID 41209699, 2025). "Furthermore, SDC1 can promote the progression of triple-negative breast cancer by activating the c-src/FAK signaling pathway." (PMID 38728370, 2024). "Therefore, we suppressed Sdc-1 expression using siRNA knockdown (KD) in the triple-negative breast cancer cell line MDA-MB-231 to assess its effect on the TF pathway in conjunction with various cytokine treatments, referring to the role of Sdc-1 as a co-receptor for these pathways." (PMID 36980251, 2023). "Moreover, SDC1 could enhance triple-negative breast cancer (TNBC) progression by activating the c-src/FAK signaling pathways." (PMID 37564657, 2023). "In order to explore this question, we conducted an analysis of SDC1 resistance to FDA-approved drugs using the GSCA online database and reviewed the Triple Negative Breast Cancer Treatment Guidelines from 2024." (PMID 41209699, 2025). "For triple-negative breast cancer (TNBC), Syndecan-1 (CD138) and PD-L1 hold promise as prognostic markers." (PMID 39335124, 2024). "Since EGFR is known to be in a crosstalk with Notch signaling in different tumor entities including triple negative breast cancer, we examined the effect of GSI on expression of EGFR transcript levels in control and Syndecan-1-depleted SUM-149 cells." (PMID 28270211, 2017). "Another study showed that targeting SDC1/CD138 by employing immuno-PET imaging and radioimmunotherapy (RIT) using the radiolabeled antihuman SDC1 B-B4 significantly induced tumor regression in a xenograft model of triple-negative breast cancer." (PMID 36980680, 2023). "Since we previously showed that Sdc-1 KD had a negative effect on the CSC phenotype of triple-negative breast cancer cells, we explored the impact of Sdc-1 KD and HA treatment on this tumoral feature." (PMID 34070901, 2021).
mesothelioma (22 papers, 2009 to 2025). A usually malignant and aggressive neoplasm of the mesothelium which is often associated with exposure to asbestos. "Nuclear translocation of SDC1 has been linked to reduced proliferation of mesothelioma cells and occurs in a tubulin-dependent manner." (PMID 34208075, 2021). "Presence of syndecan-1 is associated with favorable outcome in lung cancer and mesothelioma, but it can also promote the growth of other tumor types." (PMID 26420915, 2015). "Considering this, syndecan-1 was proposed as a putative diagnostic marker in distinguishing mesotheliomas from metastatic adenocarcinomas." (PMID 26420915, 2015). "Syndecan-2 is a membrane bound proteoglycan associated with mesenchymal tissues while syndecan-1, in contrast, is a marker for adenocarcinoma as compared to mesothelioma." (PMID 23991032, 2013). "Our previous data suggest a complex role of syndecan-1 in mesothelioma cell proliferation although the exact underlying molecular mechanisms are not completely elucidated." (PMID 23144729, 2012). "Some overexpressed genes were confirmed by immunohistochemistry and genes encoding proteins overexpressed in mesothelioma were also overexpressed here (e.g. Ki67, Syndecan 1, Survivin and Vitronectin)." (PMID 19662092, 2009). "Univariate Cox regression analyses indicated that high SDC1 expression was significantly associated with poor OS in BRCA, GBM, LGG, Mesothelioma (MESO) and PAAD." (PMID 41364407, 2025). "Nuclear localization of syndecan-1 has also been demonstrated by others in mesothelioma cells, hepatocytes, and corneal fibroblasts, with suggested functions in the regulation of cell proliferation, synthesis of RNA, and splicing." (PMID 38891079, 2024). "Pleural effusions from mesothelioma patients showed that Vascular Endothelial Growth Factor (VEGF) levels correlate to soluble SDC-1 levels and have prognostic value." (PMID 33562126, 2021). "Proteomic analysis of the nuclear Sdc-1 interactome of mesothelioma cells identified proteins interacting with nuclear proteins and associations with pathways related to cell proliferation, RNA synthesis, splicing and cellular transport." (PMID 33922532, 2021). "Our studies highlight the effects of syndecan-1 overexpression on growth factor secretion of mesothelioma cells which inhibits endothelial cells proliferation, tube formation, and migration." (PMID 33562126, 2021). "Co-immunoprecipitation experiments with Sdc1 in mesothelioma cells have identified a large number of interactive proteins." (PMID 33922532, 2021). "In this study, suppression of TSP-1 by SDC-1 over-expressing mesothelioma cells is in line with decreased angiogenesis, supporting the latter observation." (PMID 33562126, 2021). "Intriguingly, we recently found that SDC1 interacts with a large number of nuclear proteins in human mesothelioma cells including proteins involved in RNA splicing and ribosomal biogenesis." (PMID 34208075, 2021). "In conclusion, SDC-1 over-expression affects the angiogenic factor secretion of mesothelioma cells and thereby inhibits endothelial cells proliferation, tube formation, and wound healing." (PMID 33562126, 2021). "We have previously shown that upregulation of the SDC-1 hampers mesothelioma cell growth and cell cycle progression and also affects mesenchymal tumor cell adhesion and migration." (PMID 33562126, 2021). "In mesothelioma cells TGF-β inhibited the nuclear translocation of syndecan-1, and this inhibition hampered the proliferation of the cells." (PMID 29216821, 2017). "Studies of the expression of SDC1 protein in mesothelioma tumors and cell lines revealed strong SDC1 expression in epithelial mesotheliomas and in epithelial components of biphasic mesotheliomas, while expression was reduced during sarcomatoid differentiation." (PMID 26293675, 2015). "Generally adenocarcinomas show higher cell surface and soluble syndecan-1 levels than mesotheliomas, the latter indicating worse prognosis." (PMID 26420915, 2015).
mesothelioma (continued). "Overexpression of syndecan-1 induces epithelial morphology and inhibits proliferation in mesothelioma cell lines, indicating a syndecan-1 dependent differentiation along the epithelial mesenchymal transition axis in this cancer." (PMID 25147801, 2014). "List of genes encoding proteoglycans and heparan sulfate biosynthetic enzymes affected by syndecan-1 overexpression in a mesothelioma cell line." (PMID 24392351, 2013). "Biochemical markers significantly associated with mesothelioma were hyaluronan (odds ratio, 95% CI: 8.82, 4.82–20.39), N-ERC/mesothelin (4.81, 3.19–7.93), CERC/mesothelin (3.58, 2.43–5.59) and syndecan-1 (1.34, 1.03–1.77)." (PMID 23991032, 2013). "In mesothelioma cells syndecan-1 influenced major growth factor pathways and many of these pathways were altered at multiple levels." (PMID 23144729, 2012). "In mesothelioma the expression of syndecan-1 correlates to epithelioid morphology and inhibition of growth and migration." (PMID 23144729, 2012). "We modulated the expression of syndecan-1 in a human mesothelioma cell line via both overexpression and silencing, and followed the transcriptomic responses with microarray analysis." (PMID 23144729, 2012). "Our previous study showed that syndecan-1 overexpression hampers proliferation in mesothelioma cells." (PMID 23144729, 2012). "On the other hand, when given to mesothelioma cells, TGFβ2 delayed the nuclear transport of syndecan-1 in parallel with an antiproliferative effect." (PMID 23144729, 2012). "The aim of this study is therefore to disclose critical genes and pathways affected by syndecan-1 in mesothelioma; in order to better understand its importance for tumor cell growth and proliferation." (PMID 23144729, 2012). "In order to interpret alterations generated by syndecan-1 in mesothelioma cells, we combined traditional strategies of gene expression analysis with a novel network enrichment analysis, which takes into account functional coupling in gene networks." (PMID 23144729, 2012). "Syndecan-1 is less abundant at the surface of mesothelioma cells, and the most prominent syndecan-1 reactivity is seen in the nucleus and in the mitotic spindle during mitosis." (PMID 19802384, 2009). "Syndecan-1 gives faint immunocytochemical staining at the cell surface of the mesothelioma cells, detectable amounts being seen only at cell confluence." (PMID 19802384, 2009). "Interestingly, in mesothelioma Sdc-1 promotes an arrest in the G1 phase by modifying the heparan sulfate composition." (PMID 35155241, 2022). "By over-expressing and silencing SDC-1 in mesothelioma cells, we could elicit changes in a wide range of angiogenesis-related proteins secreted to the conditioned media." (PMID 33562126, 2021). "In mesothelioma, the nuclear translocation of the HSPG syndecan-1 was linked to specific points of the cell cycle through interactions with microtubule structures, and drug-induced cell division arrest in the G2 phase inhibited the HSPG syndecan-1 translocation to the nucleus." (PMID 34671250, 2021). "To study these mechanisms, we have used one mesothelioma cell line where the expression of SDC-1 could be modulated." (PMID 33562126, 2021). "The results showing that knockdown of SDC1 resulted in reduced E-cadherin levels are in line with recent studies in mesothelioma cells, and may indicate that SDC1 plays a role in regulating the activity of several core EMT-TFs." (PMID 34208075, 2021). "The low expression in mesothelioma as compared to the high prevalence of strong expression in pulmonary adenocarcinoma suggests that Syndecan-1 could be potentially added to the long list of antibodies that help to distinguish these tumor entities." (PMID 31976021, 2019). "Presence of syndecan-1 is related to differentiation state of mesothelioma cells." (PMID 26420915, 2015).